CD4 (CD4 molecule)
Diseases named in the same sentence as CD4 in open-access papers (continued):
Sharing a sentence is not in itself a finding about the gene and the disease.
lung cancer (498 papers, 2006 to 2026). A malignant neoplasm involving the lung. "Age ≥65 years, history of smoking, elevated LMR, and an elevated CD4+/CD8+ ratio are independent risk factors of lung cancer." (PMID 40761783, 2025). "Subsequent multivariate logistic regression analysis demonstrated that age ≥65 years, history of smoking, lower LMR, and lower CD4+/CD8+ ratio were independent risk factors for the occurrence of lung cancer occurrence in patients with IgE >100 IU/ml." (PMID 40761783, 2025). "In patients with HIV (Human Immunodeficiency Virus), the low number of CD4+ lymphocytes and the decreased CD4+/CD8+ ratio have been correlated with increased risk of lung cancer as a result of the deficient immune response." (PMID 40731892, 2025). "In particular, elevated pretreatment levels of circulating CD4+CCR9+ and CD4+CCR10+ T cells have been associated with significantly poorer overall survival in patients with advanced lung cancer undergoing anti-PD-1 immune checkpoint inhibitor (ICI) therapy." (PMID 41149503, 2025). "Balancing out the influence of sample size (number of cases), we found that genes expressed in CD4+ T cells were more likely to affect risk of lung cancer (OR of Fisher's exact test = 1.7, p = 3.66 × 10−5) and cervical cancer (OR = 4.7, p = 4.12 × 10−12)." (PMID 41216857, 2025). "We note, however, that the effect of CD4:CD8 ratio on the risk of lung cancers remained after adjusting for bacterial pneumonia episodes in the US Veteran study." (PMID 38092042, 2024). "The association between the presence of FOXP3+ CD4+ T cells in TILs has been extensively studied in all subtypes of lung cancer." (PMID 38674427, 2024). "This concept gains support from existing research, where IL-38 expression was significantly associated with CD8+ tumour-infiltrating lymphocytes in lung cancer, and IL-38 was shown to potentially impact the further differentiation of CD4+ T cells." (PMID 38533512, 2024). "A low CD4:CD8 cell ratio was associated with an increased risk of lung cancer in the US Veteran cohort study, and a higher risk of Kaposi sarcoma and non-Hodgkin lymphoma in the COHERE cohort study." (PMID 38092042, 2024). "Nevertheless, a cohort study involving more than 80,000 people reported that HIV patients with a low amount of CD4+ Th cells had an increased risk of lung cancer." (PMID 38542056, 2024). "Another study showed that lung cancer patients with the L858R EGFR mutation had more inflammatory tumors with higher CD4 and CD8+ T cell expressions compared to those with the exon 19 deletion mutation." (PMID 37033978, 2023). "Another study found that HIV-positive individuals with a low CD4 count, indicating more advanced immune suppression, had a higher risk of lung cancer than those with a higher CD4 count." (PMID 37298092, 2023). "Studies have shown that antigen-presenting cancer-associated fibroblasts in lung cancer can activate CD4 T cells to play the role of immune stimulation." (PMID 37607935, 2023). "Lung cancer mortality risk increased with active or past smoking, heterosexual contact as transmission route, and CD4 counts < 500/μL; liver cancer mortality was associated with injected drugs or heterosexual contact as transmission route." (PMID 38008809, 2023). "Nevertheless, other studies showed higher risk of lung cancer associated with low CD4/CD8 ratio even after accounting for smoking status." (PMID 35428209, 2022). "Two of the most studied TILs that are believed to be associated with the early stages of lung cancer are CD4 and CD8, commonly known for their important roles in the regulation of both antitumor and protumorigenic processes." (PMID 35628157, 2022). "In another study, it was demonstrated that high-risk in patients with lung cancer was associated with significantly high levels of activated memory CD4 T cells, resting NK cells and M0 macrophages." (PMID 34979926, 2022).
lung cancer (continued). "Tumor-infiltrating immune cells, such as CD8+ T cells, CD4+ T cells, B cells, tumor-associated macrophages (TAMs), are the main components of the lung cancer microenvironment." (PMID 35287670, 2022). "A high percentage of CD4+ T cells in the tumor stroma is associated with a poor prognosis in lung cancer." (PMID 36052170, 2022). "A rich CD4+ or CD8+ T cell density in the tumors was associated with a favorable clinical prognosis in lung cancer and several other types of tumors." (PMID 34181042, 2022). "In this study, we investigated gene expression profiles in intra-tumoral immune cells in lung cancer, focusing on tumor-associated macrophages, and interactions with CD4+ and CD8+ T cells." (PMID 33918618, 2021). "This study indicated that the high percentages of peripheral CD3+, CD4+ T cells and CD4/CD8 ratio were associated with longer OS in lung cancer patients." (PMID 33859531, 2021). "The development of lung cancer is linked with different factors, such as immunosuppression, CD4 count, and viral load, wherein immunosuppression is responsible for the observed higher rates of lung cancer in HIV patients." (PMID 34502312, 2021). "Studies in non‐small cell lung cancer found high infiltration of CD20 in combination with increased CD4 and CD8 cells associated with improved survival." (PMID 33481339, 2021). "Remarkably, in lung cancer patients, an increased CD4+/CD8+ T-cell ratio has been associated with a better response to an experimental EGF cancer vaccine." (PMID 32082401, 2020). "In lung cancer, CD4+ T cells were demonstrated to be associated with its progression and metastasis." (PMID 32231717, 2020). "Development of lung cancer in patients with HIV has been linked to various factors, including immunosuppression, CD4 count, and viral load, and cigarette smoking is an important risk factor for lung cancer in HIV patients." (PMID 30177858, 2018). "Wang et al9 showed that plasma IFNγ levels were significantly decreased in lung cancer patients and hypermethylation of the IFNγ promoter in CD4+ T cells was inversely associated with plasma IFNγ levels." (PMID 30039553, 2018). "In summation, the balance of these two CD4+ T cell subsets at local tumor and systemic sites appears to be strongly associated with lung cancer development, progression and prognosis." (PMID 27784305, 2016). "Conversely, RFA reportedly causes a decrease in circulating CD4+ CD25+ Foxp3+ immunosuppressive regulatory T cells (Treg) 30 days post treatment in lung cancer patients which is noteworthy since Treg counteract the function of cytotoxic CD8+ effector T cells." (PMID 26599402, 2015). "For instance, the risk of lung cancer was doubled by CD4+ T counts in the range of 350–499 cells per microliter blood compared to normal counts ≥500, and continued to increase as the CD4+ T cell count fell." (PMID 24860567, 2014). "In conclusion, decreased IFNG expression of CD4+ T cells co-cultured with lung cancer cell is associated with IFNG promoter hypermethylation." (PMID 24244422, 2013). "Our study shows that expression of TIM-3 on CD4+ TILs cells significantly associated with worse clinical pathological parameters in lung cancer." (PMID 22363469, 2012). "A strong relationship between declining CD4+ cell counts and lung cancer risk was recently reported by the French Hospital HIV Database (FHVD), with a relative risk of 4.8 (95% CI: 2.8–8.0) for 100–199 vs >500 latest CD4+." (PMID 22240797, 2012). "Several factors, including viral load, CD4+ T-cell count, immunosuppression, and smoking, have been linked to development of lung cancer in these patients." (PMID 23118782, 2012). "CD4-positive T cells, along with their related cytokines, are associated with lung cancer risk." (PMID 35814479, 2022). "In addition, GNPNAT1 is associated with immune infiltration in lung cancer, which has a converse correlation with infiltration of B cells, CD4+ T cells, and dendritic cells, all of which have antitumor effects in NSCLC." (PMID 36408131, 2022).
lung cancer (continued). "Furthermore, we recently reported that the presence of circulating tumor-specific CD4 Th1 was associated with better prognosis in lung cancer patients, notably in patients with localized disease." (PMID 35546670, 2022). "In humans, the importance of CD4+ T cells in preventing lung cancer is indirectly suggested by the observations that HIV-infected patients have a higher incidence of lung cancer, and lung cancer risk in HIV patients was shown to be associated with low CD4+ T cell counts." (PMID 34868011, 2021). "Moreover, the increased risk of lung cancer in HIV patients is correlated with a low CD4 cell count, viral load, and increased bacterial pneumonia episodes." (PMID 34502312, 2021). "Therefore, mutations in DNA repair genes in lung cancer were linked to increased TILs as CD4+ and CD8+ in the tumor." (PMID 31658756, 2019). "A report from the French HIV Database Study reported an inverse relationship between lung cancer risk and CD4 counts and an elevated risk of lung cancer was observed among HIV-infected individuals with CD4+ cells counts below 200 μL in an integrated health care system in the US." (PMID 27882054, 2016). "Similarly, they were able to protect up to 60-70% of the CD4+ T cell-deficient mice, and in mice that developed tumors only fewer lung malignant tumor colonies were observed." (PMID 23785406, 2013). "A CD4+/CD8+ ratio lower than 25 within 1 year of lung cancer diagnosis showed an association with lung cancer risk of borderline statistical significance (OR=2.15, 95% CI: 1.00–4.59), but this relationship was not seen at 1–2 years before lung cancer diagnosis (OR=1.07, 95% CI: 0.49–2.36)." (PMID 22240797, 2012). "A recent prospective French study involving 52,278 patients followed up between 1998 and 2006 has shown that at a CD4 count below 500 cells/mm3, the cancer risk (Hodgkin's lymphoma, liver and lung cancer) progressively increased: the highest risk was when CD4 count was below 50 cells/mm3." (PMID 21443771, 2011). "Notably, CTSG has been associated with CD4 T cell activation in lung cancer." (PMID 39891665, 2025). "This agrees with the literature: CD4+ T cells primarily mediate anti-tumor immunity and are associated with favorable prognosis in lung cancer patients; B cells also show anti-tumor functions in all stages of human lung cancer development and play an essential role in anti-tumor responses." (PMID 38741183, 2024). "Thus, the TIM-3 expression on CD4+ TILs is associated with lung cancer progression." (PMID 22363469, 2012). "CD4+ T cells in the MPE displayed co-expression of IhRs in a similar fashion to CD4+ TILs in lung cancer." (PMID 41574275, 2026). "Targeting of Blimp-1 in T cells emerges as a novel concept to suppress immune evasion in lung cancer by regulating CD4+, CD8+and Treg function in the lung." (PMID 41984247, 2026). "The diagnostic efficacy of combining the CD4+/CD8+ ratio and nCD64 index for differentiating lung cancer from pulmonary infection was further analyzed." (PMID 42124411, 2026). "In this study, we phenotyped the CD8+ and CD4+ T cell subsets found in lung cancer MPE using flow cytometry and single cell RNAseq with a focus on TRM." (PMID 40285480, 2025). "The risk of lung cancer decreased by 22.3% for every 1-unit increase in LMR (OR = 0.777, 95% CI = 0.678–0.890; P <0.001) and by 41.8% for every 1-unit increase in the CD4+/CD8+ ratio (OR 0.582, 95% CI 0.503–0.674; P <0.001)." (PMID 40761783, 2025). "By silencing TGF-β, these nanoparticles decrease regulatory T-cell (Treg) activity and enhance CD4+ Th1 polarization, improving tumor control in lung cancer models." (PMID 40860882, 2025). "Patients with early-stage non–small cell lung cancer who relapsed after neoadjuvant αPD-L1 therapy revealed low CD4+ T cell densities in the tumor core." (PMID 40561008, 2025). "Regarding non‐small cell lung cancer, responders to immune checkpoint inhibitors exhibit elevated circulating CD4+ and CD8+ T‐cell proportions." (PMID 39749673, 2025).
lung cancer (continued). "Conversely, in non–small cell lung cancer, apCAFs activate and sustain CD4+ T cells, promoting antitumor immunity." (PMID 41055954, 2025). "A Korean cohort study indicated that patients with lung cancer undergoing ICI therapy had a lower risk of VZV infection, possibly due to the enhanced function of VZV-specific CD4+ and CD8+ T cells." (PMID 40861664, 2025). "In the pulmonary TME, dysregulated immune profiles—marked by decreased CD4+, increased CD8+, and a reduced CD4+/CD8+ ratio—are observed in lung cancer patients." (PMID 41394845, 2025). "It was observed that ZBTB46 expression correlated significantly positively with all types of immune cells analyzed, including B-cells, CD8+ T-cells, CD4+ T-cells, macrophages, neutrophils, and dendritic cells in lung cancer." (PMID 40780118, 2025). "In line with our findings, recent papers reported that lung cancer patients with a high CD8+T cells/CD4+Tregs ratio at tumor baseline showed prolonged OS after PD-1/PD-L1 blockade." (PMID 40426949, 2025). "Increasing the time-updated CD4 count reduced mortality by 15–40% (per 100 cells/μL) after NHL and anal and lung cancers and reduced CCO risk by 17–28% after KS and NHL." (PMID 41463249, 2025). "Lung cancer bone metastases create senescent, pro-angiogenic niches involving senescent-like tumor cells, stressed CD4+ T cells, and endothelial-to-mesenchymal transitions." (PMID 40658744, 2025). "A higher time-updated CD4 count (per 100 cells/μL increment) was associated with reductions in mortality of 40%, 17% and 15% for NHL, anal cancer and lung cancer, respectively." (PMID 41463249, 2025). "Ex vivo immune profiling of peripheral blood from 60 patients with advanced lung cancer reveals that UCPVax selectively activates CD4+ T cells in vivo across a broad HLA-DR restriction." (PMID 40543509, 2025). "The T cells predominated in lung cancer immune landscape, and CD4+ T cells and CD8+ T cells were the common prevalent T cell subtypes." (PMID 40070576, 2025). "CD8+ T cells alter the lung cancer microenvironment and facilitate the migration of CD4+Foxp3+ Tregs to the tumor bed." (PMID 40553564, 2025). "In lung cancer, CD4+ T cells present intracellular C3 cleavage by cathepsin and C3a signaling inhibits the production of multiple cytokines by CD4+ T cells, independently of FOXP3+ Tregs." (PMID 40370471, 2025). "In recent years, the roles and interactions of Th17 and Treg cells, two major subsets of CD4+ T lymphocytes, have garnered significant attention in the context of lung cancer, particularly non-small cell lung cancer (NSCLC)." (PMID 41562084, 2025). "CD69 and CD103 are also highly co-expressed on TRM from lung cancers, however we only saw co-expression on 10% of CD4+ TRM and 20% of CD8+ TRM." (PMID 40285480, 2025). "In non–small cell lung cancer the presence of CAFs that express meflin correlated with retained vascularization and CD4+ T-cell infiltration." (PMID 38819641, 2024). "In lung cancer, B cells, CD4 T cells, and CD8 T cells are up-regulated, while cDC, endothelial cells, fibroblasts, macrophages, and NK cells are down-regulated." (PMID 39120585, 2024). "The study findings suggest potential predictive roles for immune cell subsets and phenotypes, particularly Treg cells, HLA-DR + CD4 + T cells, and naïve CD4 + T cells, in evaluating short-term PD-1/PD-L1 therapy efficacy for lung cancer patients." (PMID 39026211, 2024). "A high absolute count of circulating CD4 Tn was an independent protective factor for progression-free survival in lung cancer." (PMID 39100667, 2024). "We further observed changes in their infiltration, and the results showed that, although COPD and lung cancer exhibited increases in various CD4 T cell subtypes compared to normal lungs, only Treg cells showed statistical significance (p-value < 0.05)." (PMID 38605291, 2024).
lung cancer (continued). "Astragalus polysaccharide (APS) treatment significantly increased the ratio of CD4+ T cell and the CD4/CD8 T cell ratio in mice with lung cancer, along with elevating blood levels of IFN-γ and IL-2." (PMID 39660124, 2024). "The median proportion of PD-1+ CD4+ or PD-1+ CD8+ T cells was found to be higher in patients with interstitial lung disease compared to patients with lung cancer." (PMID 39325190, 2024). "Here Jurkat CD4+-T-cell line was activated before co-culturing with lung cancer cell lines to assess their responsiveness to anti-PD-1 treatments." (PMID 38951894, 2024). "We observed a superior reduction in the amount of viable immune cells, as well as reductions in the percentage of CD4+ T-cells in co-cultures with ser/gly producing NKX2-1 lung cancer cells." (PMID 38160212, 2024). "Turnip considerably reduced the development of Lewis lung cancer cells in mice models of lung cancer and raised the amounts of B cells, CD4 T cells, CD8 T cells, and activated CD8 T cells in the spleens." (PMID 39594117, 2024). "While CD4 is the primary receptor for IL-16, certain cells can respond to IL-16 through alternative receptors like CD9, for example, mastocytes or lung cancer cells, as well as via CD4- and CD9-independent mechanisms." (PMID 39408600, 2024). "A retrospective study involving 74 patients with advanced non‐small cell lung cancer during immunotherapy demonstrated prolonged OS with elevated levels of CD3+/CD4+ and CD8+ T cells and reduced levels of NK cells." (PMID 38894548, 2024). "The efficacy of CD4+ T cells in the peripheral blood of lung cancer patients has been correlated with improved anti-tumor responses." (PMID 38408977, 2024). "Leptin dose-dependently promotes naïve CD4+ T cell proliferation and polarizes CD4+ T cells towards a Th1 phenotype, which in turn facilitates lung cancer secretion of inflammatory cytokines such as TNF-α and IL-6, promoting lung cancer bone metastasis." (PMID 38571500, 2024). "Our study showed that low levels of HLA-DR + CD4 + T cells and Treg cells, and high levels of naive CD4 + T cells can predict a positive outcome (CR) for lung cancer patients after treatment." (PMID 39026211, 2024). "Several studies have shown that these two CD4+ T cell subgroups play an active role in promoting lung cancer progression and metastasis." (PMID 39735532, 2024). "Immune cells related to lung cancer include CD4 + T cells, CD8 + T cells, granulocytes, monocytes, B cells, and NK cells." (PMID 38974912, 2024). "Patients with lung cancer undergoing IT alone have been shown to acquire an exhausted CD4 T cell phenotype based on expression of inhibitory receptors." (PMID 39257577, 2024). "In this study, Th7R was the only cluster in which we detected significant CXCL13 gene expression in all CD4+ T-cell clusters in the lung cancer microenvironment." (PMID 37476074, 2023). "Some studies have reported that patients with lung cancer or hepatocellular carcinoma have more CD4+T cells than do healthy individuals." (PMID 37346066, 2023). "AOC3 is an endothelial adhesion protein, and low-level AOC3 facilitated mesenchymal transformation and decreased CD4+ T cell recruitment to lung cancer." (PMID 38084139, 2023). "Patients with lung cancer who had an abundance of intra-TLS B cells had an elevated CD4+ TCR clonality and a heightened T cell-dependent B cell response." (PMID 37868967, 2023). "In agreement with our data, anti–PD-1 treatment of an autochthonous lung cancer mouse model increases IL-17A–producing γδ T cells and CD4+ T cells, which correlates with suppression of cytotoxic CD8+ T cells." (PMID 36480166, 2023). "Although memory CD4+ T cells have been proven to possess the ability of tumor suppression in TME of lung cancer, this can also be an adverse prognostic factor in lung cancer." (PMID 36507553, 2023).